PER2 (period circadian regulator 2)
Diseases named in the same sentence as PER2 in open-access papers (continued):
Sharing a sentence is not in itself a finding about the gene and the disease.
advanced sleep phase syndrome (18 papers, 2007 to 2024). A very rare circadian rhythm sleep disorder characterized by very early sleep onset and offset possibly resulting in emotional and physical disruptions. "On the other hand, phosphorylation of PER2 at different sites modulates the period length and mutations associated with differential phosphorylation of human PER2 underlies familial advanced sleep phase syndrome." (PMID 35921354, 2022). "For example, Advanced Sleep Phase Syndrome arises from mutations in the molecular clock genes Period 2 (PER2), Period 3 (PER3), and CSNK1D." (PMID 29016847, 2017). "In humans, a mutation in the PER2 gene has been shown to cause the familial advanced sleep phase syndrome (FASPS)." (PMID 20187847, 2010). "Loss of PER2 S662 phosphorylation (typically the result of a PER2 S662G substitution) causes human Familial Advanced Sleep Phase Syndrome (FASPS) which is characterized by a dramatically shortened circadian period with a 4-h advance of sleep, temperature, and melatonin rhythms." (PMID 34257372, 2021). "In addition, mutations in PER2 have been linked with advanced sleep phase syndrome, while mutations in CSNK1D and CRY1 have been linked to delayed sleep phase syndrome." (PMID 29230328, 2017). "Familial advanced sleep phase syndrome (FASPS) is caused by a T44A mutation in CK1δ that leads to hypophosphorylation of PER2 and shortens the circadian period." (PMID 39534813, 2024). "One of the sites phosphorylated by CK1ε within human PER2 is mutated in the Familial Advanced Sleep Phase Syndrome (FASPS)." (PMID 31687929, 2019). "To analyse Per1-Per2 cooperative roles at the cell culture level, we established a Per2 knockout-rescue system, which can detect period shortening in a familial advanced sleep phase syndrome (FASPS) mutant." (PMID 27609640, 2016). "Genetic variation in PER2 has been associated previously with advanced sleep phase syndrome (ASPS); additionally, Per2 knockout mice have initially diminished delta activity in response to sleep deprivation." (PMID 24635757, 2014). "In humans, point mutations in both CK1δ (NP_001884) and its substrate, PERIOD 2 (PER2 (NP_073728)), have been shown to cause familial advanced sleep phase syndrome." (PMID 22384121, 2012). "Conversely, a compound that targets PER2 specific induction might be used to delay the clock at any zeitgeber time, which would be useful for the treatment of advanced sleep phase syndrome." (PMID 33684114, 2021). "PER1 and PER2 were reported to be associated with advanced sleep phase syndrome in a British population, but not in a Japanese family." (PMID 33412754, 2020). "Serine to glycine mutation in PER2 and mutation in casein kinase Iδ gene (CSNK1D) develop familial advanced sleep phase syndrome (FASPS) whereas point mutation in PRNP causes fatal familial insomnia (FFI)." (PMID 29607311, 2018).
sleep disorder (15 papers, 2010 to 2025). A change from the patient's baseline sleeping pattern, in the hours slept and/or an alteration/dysfunction in the stages of sleep. "BPSD in the patients’ group were evaluated with NPI, PHQ-9 and the sleeping disorders questionnaire; then, they were analyzed for associations with the genetic variants of PER2, PER3, OX2R and APOE." (PMID 36901420, 2023). "The rs10462028 and rs11932595 of the CLOCK gene, the rs934945 of the PER2 gene, and the distribution of genotypes and allele frequencies of each genotype, as well as allele frequency, were significantly different in the sleep-disordered group and the normal-sleep group (both p < 0.001)." (PMID 40951374, 2025). "For example, familial advanced sleep phase syndrome (FASPS), a sleep disorder characterized by recurrent patterns of early evening sleepiness and early morning awakening, is associated with a mutation in PER2 that leads to its faster degradation and a shorter circadian period." (PMID 32993432, 2020). "Previous studies have primarily focused on CLOCK and PER2 in sleep disorders, but RORA’s role remains underexplored, particularly in mental worker populations." (PMID 40951374, 2025). "Abnormal expression levels of Per2, Clock, and Bmal1 in oral mucosa and mononuclear cells at certain time points were detected in patients with sleep disorders after TBI." (PMID 38285094, 2024). "We found that the expression of Per2, Clock, and Bmal1 in oral mucosal cells and peripheral blood monocytes in patients with sleep disorders after craniocerebral injury was significantly lower than that in patients with normal sleep after craniocerebral injury." (PMID 36303945, 2022). "Our data suggests that the alterations of genes associated with circadian rhythm such as Per2 and Npas4 due to the influences of ELS may trigger sleep disorders." (PMID 34795694, 2021). "Correlation study of CLOCK, PER2, and RORA genes with sleep disorders." (PMID 40951374, 2025).
oral squamous cell carcinoma (14 papers, 2020 to 2025). "The loss of PER2 expression is closely associated with the genesis and development of oral squamous cell carcinoma." (PMID 38334624, 2024). "PER2 inhibits the proliferation of oral squamous cell carcinoma and promotes the apoptosis of OSCC cells, which is dependent on the PI3K/AKT/mTOR signaling pathway." (PMID 37069338, 2023). "In the previously cited literature, Per2 was shown to be involved in the progression of oral squamous cell carcinoma through the PI3K/AKT/mTOR pathway." (PMID 35599595, 2022). "Oral squamous cell carcinoma, one of the most prevalent cancer types in the world, has been confirmed under the influence of a key circadian gene, PER2, whose role has been identified in the development of some other types of cancers." (PMID 32185221, 2020). "Furthermore, the PI3K/AKT/mTOR pathway is affected by Per2 in oral squamous cell carcinoma, demonstrating that Per2 is a tumor suppressor in multiple mechanistic investigations." (PMID 35599595, 2022). "Aberrant expression of PER2 promotes the progression of oral squamous cell carcinoma, and upregulated expression of NR1D1 may promote the development of renal clear cell carcinoma." (PMID 34977153, 2021). "However, the biological functions and mechanism of Per2 in OSCC (OSCC: oral squamous cell carcinoma) remain unclear." (PMID 32284762, 2020). "The tumour- suppressive effect of per2 was demonstrated in oral squamous cell carcinoma (OSCC), as per2 silencing inhibited autophagy, apoptosis and increased the proliferation rate." (PMID 36361993, 2022). "For example, overexpression of PER2 induces decreased proliferation and increased apoptosis by promoting autophagy in OSCC (oral squamous cell carcinoma) cells." (PMID 34977153, 2021). "Per2 mRNA and protein expression levels were detected by RT-qPCR and western blotting in normal oral mucosal HOMEC cells and oral squamous cell carcinoma TSCCA, SCC15 and CAL27 cells." (PMID 32284762, 2020).
leukemia (13 papers, 2008 to 2025). A malignant (clonal) hematologic disorder, involving hematopoietic stem cells and characterized by the presence of primitive or atypical myeloid or lymphoid cells in the bone marrow and the blood. "Previous reports have suggested that the ablation of the Period 2 gene (Per 2) leads to enhanced development of lymphoma and leukemia in mice." (PMID 18334030, 2008). "It was also found in leukemia cells that non-coding variants at KRAS and PER2 enhancers affect the binding of nuclear receptor family TFs PPARG and RXRA, which disturbs the expression of KRAS and PER2 and promotes the growth of leukemia cells." (PMID 39724337, 2025). "Similar effects were also seen when Per2 was knockdown in human leukemia cells." (PMID 32437452, 2020). "Taken together, these data suggest an important cancer participation of an altered expression of miR-650 through 22q11.2 alterations by targeting different TSG, such as PER2 in leukemias and lymphomas, THBD in thyroid cancer, and both of them plus STAT5 in BRCA." (PMID 33086498, 2020). "This is consistent with studies in Per2-overexpressing leukemia cells." (PMID 25760074, 2015). "In leukemias, PER2 (period circadian clock 2) was identified as a downstream target of C/EBPα and had its genitive impact in promoting AML initiation." (PMID 29692408, 2018).
prostate carcinoma (13 papers, 2012 to 2025). A carcinoma that arises from epithelial cells of the prostate gland. "Zhu and Colleagues found a difference in risk association of rs7602358 with prostate cancer between less aggressive and more aggressive prostate cancer subgroup, leading to suppose a role of PER2 in malignant cells aggressiveness." (PMID 30518396, 2018). "In vitro administration of melatonin resulted in an increase in Clock and Per2 levels and a concurrent decrease in Bma11, effectively “re-synchronizing” the once dysregulated circadian rhythm circuitry seen in the prostate cancer cells." (PMID 37191417, 2023). "Epidemiological studies of night shift workers provide strong evidence for the association between prostate cancer and gene variants, including BMAL1, NPAS2, CRY2 and PER2." (PMID 36291899, 2022). "Per2 protein levels were found to be downregulated in proliferative prostate cancer cells compared to normal prostate cells, whereas melatonin treatment resulted in a resynchronization of oscillatory circadian rhythm genes (Dbp and Per2)." (PMID 33371502, 2020). "Our findings extend previous studies showing that overexpression of Per1 and Per2 promotes apoptosis by altering the expression of apoptosis-related genes, including in prostate cancer cells." (PMID 25760074, 2015). "Conversely, flutamide, an anti-prostate cancer drug and apoptosis inducer, up-regulated Per2 gene expression in prostate mesenchymal cells." (PMID 25628599, 2014). "Further, the results demonstrated that Tmprss2 was significantly involved in the “prostate cancer” KEGG pathway, as well as in the “import into cell” term with Per2, Atp1a1, and Arrb1 (GO:0098657, FDR = 3.39 × 10−5)." (PMID 34834564, 2021).
ischemia (11 papers, 2013 to 2025). A hypoperfusion of the BLOOD through an organ or tissue caused by a PATHOLOGIC CONSTRICTION or obstruction of its BLOOD VESSELS, or an absence of BLOOD CIRCULATION. "In our analysis, loss of Per2 from the retina has a similar effect on neovascularization, suggesting that inactivation of the dysregulated clock can be protective against ischemia induced neovascularization." (PMID 35933488, 2022). "Specifically, Per2 and Cav1 have been shown to promote microglial polarization and inflammatory responses, which are essential for mitigating brain injury following ischemia." (PMID 40292254, 2025). "PER2 is a central regulator of circadian rhythms and has been shown to elicit endogenous cardioprotection from ischemia." (PMID 34681805, 2021). "The observation that delayed cerebral ischemia as well as early mortality after SAH were associated with relatively lower CSF Per2 expression levels on day 7/day 1 respectively could support the existing preclinical data demonstrating Per2-dependent cardio- and neuroprotection from ischemia." (PMID 33562664, 2021). "It has been shown that Per2 promotes circadian stabilization of HIF-1α activity that is critical for myocardial adaptation to ischemia." (PMID 25375852, 2014). "The inability of Per2−/− mice to down regulate enoyl-CoA hydratase during ischemia therefore implies changes in cardiac fatty acid levels." (PMID 23977055, 2013). "Here, we found a novel role of Per2 in controlling fatty acid metabolism and inflammation during ischemia and reperfusion, respectively." (PMID 23977055, 2013). "The main finding of our study is that Per2 activation during ischemia regulates fatty acid beta-oxidation during ischemia and inflammation during reperfusion." (PMID 23977055, 2013). "Interestingly, we observed that ischemia decreased mitochondrial Per2 content in the heart compared to controls." (PMID 38221535, 2024). "Thus, Per2 stabilization through adenosine activation of Adora2b or by exposure to intense light modified HIF-dependent cardiac metabolism, resulting in the transcriptional induction of glycolytic enzymes and Per2-dependent protection from ischemia." (PMID 32121234, 2020). "Activation of PI3K/Akt signaling was regulated by per2, which was induced by ischemia." (PMID 25268972, 2014).
type 2 diabetes (11 papers, 2009 to 2025). "In contrast, the minor allele (G) of rs7602358 near the PER2 locus appeared to confer protection against type 2 diabetes in both the UKADS (p = 0.003) and DGP (p = 0.004) datasets (combined cohort, p = 3.18×10−5)." (PMID 22485135, 2012). "The rs7602358G allele near PER2 was negatively associated with type 2 diabetes in our Punjabi cohorts (combined odds ratio [OR] = 0.75 [0.66–0.86], p = 3.18×10−5), while the BMAL1 rs11022775T allele was associated with an increased risk of the disease (combined OR = 1.22 [1.07–1.39], p = 0.003)." (PMID 22485135, 2012). "PER2 mRNA levels were unaltered in the type 2 diabetes group, but a significant decrease in PER2 protein expression was observed in the type 2 diabetes group (p<0.05)." (PMID 38981930, 2024). "Another recent study demonstrated that administration of metformin, one of the most commonly used drugs for type 2 diabetes, leads to the degradation of PER2 and to a phase advance in the circadian gene expression." (PMID 19470168, 2009). "Moreover, expression levels of per2 and cry2 were significantly lower in islets from human donors with type 2 diabetes and mRNA expression levels of per1 and per2 were significantly lower in the leucocytes of patients with type 2 diabetes than in non-diabetic controls." (PMID 24736612, 2014). "Our data demonstrate a dysregulation of the molecular clock system in PBMCs from participants with type 2 diabetes, manifested by a decrease in CLOCK, CRY1, p-BMAL1 and PER2 protein levels and an increase in BMAL1 and NR1D1 mRNA levels." (PMID 38981930, 2024). "Impairment of the circadian clock genes such as CLOCK, BMAL1, cryptochrome (CRY1 and CRY2), and period (PER1, PER2, and PER3) contributes to the decrease in glucose tolerance, defective β-cell function, and the development of type 2 diabetes." (PMID 28352282, 2017). "Indeed, when mRNA expression levels were compared between cultured human islets from deceased donors, Per2, Per3, and Cry2 were under-expressed in type 2 diabetes mellitus (T2DM) patients compared to healthy donors, alluding that metabolic function correlates with robust clock rhythms." (PMID 31555652, 2019). "On the other hand, mechanisms that impair the circadian clock genes, such as circadian locomotor output cycles kaput (CLOCK), brain and muscle Arnt-like protein 1 (BMAL1), and period genes (PER1, PER2, and PER3), contribute to defective beta-cell function and development of type 2 diabetes." (PMID 28352282, 2017). "Participants with type 2 diabetes showed increased BMAL1 and NR1D1 mRNA levels and decreased protein levels of circadian locomotor output cycles kaput (CLOCK), cryptochrome 1 (CRY1), phosphorylated basic helix-loop-helix ARNT like 1 (p-BMAL1) and period circadian protein homologue 2 (PER2)." (PMID 38981930, 2024).
bipolar disorder (10 papers, 2009 to 2025). A disorder of the brain that causes unusual shifts in mood, energy, activity levels and the ability to carry out day-to-day tasks. "Further in the line are genes participating in circadian clock function such as ARNT, ARNT2, and PER2 which have been implicated in anxiety disorders–alcohol dependence comorbidity and D-box binding protein gene (Dbp) supposedly influencing the risk for both bipolar disorder and alcoholism." (PMID 34201295, 2021). "Studies in humans have yielded evidence for an association of genetic variants of per2, per3 and cry2 with mood disorders such as SAD (seasonal affective disorder), bipolar disorder and dysthymia, respectively selective characteristics of these conditions." (PMID 26679264, 2016). "Several studies have shown association of clock gene polymorphisms with mood disorders, including associations of: MDD with Per2, Cry1, and Rora; seasonal affective disorder with Bmal1, Per2, Cry2, and Npas2; and bipolar disorder with Clock, Bmal1, Per3, Rev-erbα, and Rorb." (PMID 37441675, 2023). "Valproic acid shortened the period of mouse wheel-running activity, PER2::LUC rhythms in mouse SCN explants, PER2::LUC rhythms in mouse hippocampal cell culture, and PER2::LUC rhythms of cultured human fibroblasts from patients with bipolar disorder." (PMID 29230328, 2017). "Phase control through the melatonin-guided interval of Per1/Per2 to Cry1/Cry2 expression peaks may have relevance to mood disorders, as the internal alignment and the melatonin signal (amplitude and phase) are abnormal in patients with bipolar disorder and those with winter depression in particular." (PMID 20195522, 2010).
colitis (10 papers, 2014 to 2025). Inflammation of the colon. "On the contrary, we found that in colorectal stromal cells, colitis was associated with decreases in the mRNA levels of Arntl, Clock, Cry1, Cry2, Per2, Per3, Nr1d1, Npas2, and BBR restored the expression of these genes except Per2." (PMID 36528592, 2022). "Bone marrow chimeric mice in which the donors and/or the recipients were either wild-type or mPer2m/m mice were generated to further investigate whether the Per2 mutation in the tissue resident cells (most likely colonic epithelium) was important for the protection against DSS-induced colitis." (PMID 24845399, 2014). "Further, jetlag-induced circadian disruptions in DSS-induced colitis mice aggravated colitis, disrupted rhythms of Clock and Bmal1 expression, and reduced Per2 expression." (PMID 37711458, 2023). "Examination of C57BL/6 mice with DSS-induced colitis revealed significantly reduced Cry1, Per2, Npas2 and Rev-erbα expression, but significantly increased expression of Rorα." (PMID 37218867, 2023). "In summary, our research provides crucial evidence to confirm that circadian rhythm disruption aggravates DSS-induced colitis in mice and proves that inhibiting Per2 expression can reduce ATP production and cell proliferation." (PMID 35720196, 2022). "We also compared the expression of several key circadian genes including Arntl, Clock, Cry1, Cry2, Per1, Per2, Per3, Nr1d1, and Npas2 in colon samples collected at 03, 09, 15, and 21 of normal mice, colitis mice, normal mice receiving BBR, and colitis mice receiving BBR." (PMID 36528592, 2022). "In immune cells, colitis was associated with a decrease in expression of Per2 while the expression of other key circadian genes was not affected." (PMID 36528592, 2022). "Interestingly, this pathogenic role of decreased PER2 in human IBD appears to contrast with findings in mouse models, where mice with a mutated Per2 gene showed increased expression of tight junction proteins (occludin and claudin-1) and decreased susceptibility to DSS-induced colitis." (PMID 40332348, 2025). "In addition, UA pre-treatment by oral administration to female C57BL/6 mice showed the improvement in the fecal IgA concentrations, tight junction expression (Clnd1 and Clnd4), and clock gene expression (Bmal1 and Per2) in a DSS-induced colitis model induced using DSS treatment." (PMID 39064706, 2024). "Per2::Luciferase (Per2::Luc) mice, a protein reporter of the circadian clock that contains Luciferase fused to the Per2 gene, were treated with DSS to induce colitis." (PMID 35223537, 2022). "Intriguingly, we show that only the expression of Per2 is suppressed in the colorectal immune cells in colitis mice, which was not affected by BBR, suggesting that circadian rhythms in colonic immune cells are not a major target of BBR." (PMID 36528592, 2022). "In contrast, chimeric mice lacking Per2 in the non-hematopoietic cells were resistant to DSS-induced colitis similar to the mPer2m/m mice reconstituted with mPer2m/m bone marrow cells, as indicated by the changes of those parameters." (PMID 24845399, 2014). "However, BBR failed to rescue the expression of Per2 in colitis mice." (PMID 36528592, 2022).